BDNF (brain derived neurotrophic factor)
Diseases named in the same sentence as BDNF in open-access papers (continued):
Sharing a sentence is not in itself a finding about the gene and the disease.
Stroke (continued). "The aim of this study was to determine whether the daidzein elicits beneficial actions in a stroke model, namely, cerebral ischemia/reperfusion (I/R) injury, and to reveal the underlying neuroprotective mechanisms associated with the regulation of Akt/mTOR/BDNF signal pathway." (PMID 35095491, 2021). "Plasma BDNF levels measured on admission were lower in patients with lower BI scores (BI ≤ 80) measured at discharge (day 5 post-stroke)." (PMID 33809965, 2021). "BDNF can promote astrocytosis, microglial activation, and vascular remodeling both after stroke and in normal brain tissue." (PMID 32378029, 2021). "NTRK2 (high affinity nerve growth factor receptor) is a receptor of BDNF that is also involved in neurogenesis and neuronal plasticity; this protein has been related to stroke throughout the pathway BDNF-TrKBPI3K/Akt." (PMID 35008673, 2021). "Its role in angiogenesis, neurogenesis, brain repair, and synaptic plasticity has been unveiled through animal experiments and has established BDNF as an important component of post-stroke recovery." (PMID 33809965, 2021). "It was observed that BDNF levels during the first 24 h of stroke were significantly higher among patients under 65 years compared to older individuals." (PMID 32944919, 2021). "Nonetheless, the authors noted that PBMCs that contained BDNF measured on the third day after stroke was increased in patients with good functional outcome." (PMID 33809965, 2021). "The use of exogenous BDNF after stroke is hindered by its rapid degradation and its inability to cross the blood-brain barrier (BBB)." (PMID 34108925, 2021). "Lastly, Zhang and colleagues examined how treatment with atorvastatin correlated with the functional outcome of stroke and BDNF levels versus the control group." (PMID 33809965, 2021). "Through our qualitative review, we highlighted a potential role of BDNF measured at the acute phase of stroke as a predictor of stroke outcome." (PMID 33809965, 2021). "BDNF signal transduction plays an important role in hippocampal neurogenesis and promotes functional recovery after stroke in the perimeningeal cortex." (PMID 34759285, 2021). "In the few studies available with consecutive BDNF measurements after stroke, the findings are conflicting." (PMID 33809965, 2021). "Future studies should focus on defining the role of serum BDNF in predicting functional outcome measures from early phase up to 3–6 months after stroke." (PMID 33809965, 2021). "We conducted a thorough review of all the available data concerning the relationship between BDNF, stroke outcome, and acute stroke severity." (PMID 33809965, 2021). "BDNF promotes the survival and differentiation of NSPCs and neuroblasts in the rat striatum after stroke or injury." (PMID 34768919, 2021). "Lower serum BDNF levels in the early stage after stroke are a factor for poor recovery after stroke." (PMID 34335824, 2021). "Five out of seven studies reported a significant decrease in BDNF levels in PSD patients at a certain stage (most likely the early stage) of stroke after admission, whereas the other two showed contrasting findings." (PMID 34141514, 2021). "Astrocytes are known to modulate BDNF production as a neuroprotective mechanism in response to chemicals or stroke onset." (PMID 34455033, 2021). "We also noted that BDNF levels were significantly lower in patients with stroke compared to healthy individuals." (PMID 33809965, 2021). "This difference in sampling site likely accounts for the differences in BDNF measurements in the same striatal stroke model across these two papers." (PMID 32378029, 2021). "The functions of BDNF, including neurogenesis, neuroprotection, and neuroplasticity, can give a chance of developing and improving rehabilitation options after stroke." (PMID 33343231, 2020). "The effects of treatment with stem cells overexpressing BDNF has been evaluated following neonatal stroke." (PMID 33343501, 2020).
Stroke (continued). "The connecting factor between depression, physical impairment, and mortality in patients with stroke can be brain-derived neurotrophic factor (BDNF), a member of the neurotrophin family, involved in neuronal development, differentiation, and survival." (PMID 33213019, 2020). "Memantine improved stroke outcomes via increasing BDNF, GDNF, and VEGF levels, reducing reactive astrogliosis and enhancing vascular density." (PMID 32782018, 2020). "The relationship between white matter integrity and the brain-derived neurotrophic factor (BDNF) genotype and its effects on motor recovery after stroke are poorly understood." (PMID 33029116, 2020). "Serum BDNF levels were measured on the first day of stroke, on the 14th day, before AR-based rehabilitation (median, 45th day), and after the AR-based rehabilitation (median, 82nd day)." (PMID 32916851, 2020). "For instance, when fused to a rabies virus glycoprotein-derived peptide, BDNF was able to enter nerve cells via intravenous administration and exhibited neuroprotective effects in a mouse model of stroke." (PMID 32399020, 2020). "This means that BDNF release from the brain tissue can be modulated by changes in free fatty acids in stroke patients." (PMID 33343231, 2020). "In stroke patients significant lower BDNF levels were detected, which were positively correlated with poor functional outcome." (PMID 32117979, 2020). "The upregulation of protein kinase B (Akt) and Raf/mitogen-activated protein kinase (MAPK)/extracellular signal-regulated kinase (Erk1/2) signaling pathways as BDNF downstream factors exert possible protection in stroke." (PMID 33192177, 2020). "Nevertheless, more detailed mechanisms of the BDNF-TrkB pathway's effect on stroke recovery, or that of other brain insults, remain elusive and will require further in-depth investigation." (PMID 32399020, 2020). "In the next step of the study, we analyzed the association between inflammatory metabolites of FFAs, i.e., eicosanoids, and BDNF in stroke patients." (PMID 33343231, 2020). "A meta-analysis from 2017 suggests that a period of regular aerobic exercise increases the level of brain-derived neurotrophic factor (BDNF) in a combined sample of studies on stroke, Multiple Sclerosis, and PD." (PMID 32256559, 2020). "Three studies only examined the change in serum BDNF and stroke volume (SV) following rich-(poly)phenol supplementation." (PMID 32466148, 2020). "There is a wealth of evidence to support that BDNF are important contributors to protect neurons suffering from a stroke injury." (PMID 33101581, 2020). "The functional outcome based on the mRS examination performed on the 90th day after stroke onset was significantly worse in those patients whose BDNF level on the first day after admission was lower than 9.96 ± 5.21 ng/ml." (PMID 31701356, 2020). "BDNF is reported to have a critical role in promoting recovery after stroke as a crucial signaling molecule that mediates adaptive brain plasticity." (PMID 33275615, 2020). "Conversely, BDNF had a different profile, showing a progressive decrease of its serum levels from the stroke onset." (PMID 31768951, 2020). "Due to its role in neuronal differentiation, survival, and synaptic plasticity, BDNF has been extensively studied in stroke recovery." (PMID 33182716, 2020). "The results of animal studies showed the improvement of neurological function after stroke, assessed with the modified Neurological Severity Score, with accompanying increase in BDNF concentration." (PMID 31701356, 2020). "In this review, we aim to summarize recent progress in the research and development of stroke therapeutics, including the challenges and potential of BDNF and its downstream signaling pathways as new targets." (PMID 32399020, 2020). "A recent research reported that transplanting BMMSCs through the tail vein increased BDNF expression in the infarcted hemisphere of the brain and elicited functional recovery in rat stroke models." (PMID 32215019, 2020).
Stroke (continued). "Then, we performed the analysis to check any influence of the type of stroke according to the TOAST classification on BDNF level." (PMID 33343231, 2020). "Our previous data support that SI after stroke can lead to a decrease in BDNF, a well-known neurotrophic factor." (PMID 33374156, 2020). "To date, the role of the BDNF-TrkB pathway in mediating functional rehabilitation and recovery from stroke has been extensively investigated." (PMID 32399020, 2020). "BDNF has emerged as a key facilitator of neuroplasticity involved in motor learning and rehabilitation after stroke." (PMID 33029119, 2020). "Brain-derived neurotrophic factor (BDNF), another potential prognostic factor after stroke, is an important neurotrophin that promotes axonal growth in neuroplasticity." (PMID 33029116, 2020). "In the present study, we tried to elucidate the relationship between serum BDNF levels and motor recovery in response to AR-based rehabilitation over a 60–90-day post-stroke period, which is still considered to belong to the plastic window for stroke recovery." (PMID 32916851, 2020). "Increased BDNF levels in perilesional areas have been observed with interventions that improve functional recovery post stroke." (PMID 33275615, 2020). "The microstructural integrity of both the intra- and interhemispheric connections is differentially related to motor recovery based on the specific BDNF genotype in patients with stroke." (PMID 33029116, 2020). "The aim of this study was to analyze the potential impact of FFAs and eicosanoids on the BDNF level in stroke patients." (PMID 33343231, 2020). "Such beneficial upregulation of NGF and BDNF was accompanied by an increase in GAP-43 levels when optogenetic stimulations were provided after stroke." (PMID 33015061, 2020). "The aim of the study was to evaluate the impact of FFAs and their inflammatory metabolites on the level of BDNF in stroke patients." (PMID 33343231, 2020). "We will now summarize the major, recent findings regarding stroke treatment and try to delineate the potential therapeutic capabilities of BDNF by focusing on different aspects of a stroke's cellular and molecular mechanisms." (PMID 32399020, 2020). "In stroke patients in particular, chronically low circulating BDNF levels are correlated with the incidence of PSD." (PMID 32010477, 2020). "Brain-Derived Neurotrophic Factor (BDNF) and its rs6265 single nucleotide polymorphism (SNP) play an important role in post-stroke recovery." (PMID 33182716, 2020). "A previous study reported that a combination therapy of rehabilitation and noninvasive brain stimulation in patients with stroke induced increased BDNF secretion and improved motor function." (PMID 33029116, 2020). "In this study, differential associations between upper limb motor impairment and tract-related FA were shown to be dependent on the BDNF genotype at the subacute phase after stroke." (PMID 33029116, 2020). "In summary, how BDNF genotype and methylation can affect motor function and post-stroke rehabilitation remains uncertain." (PMID 33182716, 2020). "Consistently, Western blotting showed that protein expression levels of MBP, oxytocin, and BDNF were significantly increased in the post-ischemic brain of hypothermia group compared to stroke control group." (PMID 32010477, 2020). "Recent promising preclinical outcomes have made BDNF a popular late-stage target in the development of novel stroke treatments." (PMID 32399020, 2020). "Intranasal delivery of MSCs alone or MSCs overexpressing BDNF (MSC-BDNF) following neonatal stroke were equally effective in reducing infarct size and white matter injury, and both treatments induced cell proliferation in the injured hemisphere." (PMID 33343501, 2020). "The fourth group of potential stroke biomarkers is represented by the brain-derived neurotrophic factor (BDNF), glial cell line–derived neurotrophic factor (GDNF), and nerve growth factor (NGF)." (PMID 31701356, 2020).
Stroke (continued). "Through the activation of its downstream PI3K/Akt and MAPK/ERK pathways, BDNF is capable of protecting neurons from apoptosis, a critical event that directly leads to neuronal cell death and brain damage during stroke." (PMID 32399020, 2020). "We encourage further research into the correlation between the level of omega-3 FA and the BDNF level in stroke patients." (PMID 33343231, 2020). "Erythropoietin (EPO) is a hematopoietic cytokine that shows neuroprotective effects in stroke by enhancing angiogenesis and neurogenesis and by upregulating synaptic plasticity-related genes, including BDNF." (PMID 32399020, 2020). "Our understanding of the role of FFAs and their inflammatory metabolites in BDNF metabolism can add to the search for novel therapies in cardiovascular disorders such as stroke." (PMID 33343231, 2020). "Anti-inflammatory microglia have been reported to peak 3 days after a stroke and play an essential role in synapse remodeling through the release of microglia-derived BDNF." (PMID 32345303, 2020). "Patients of C-OPO, who were under outpatient observation after Acute Phase I of the program, had significantly lower serum BDNF and worse motor disorders on the 90th day of stroke than those of A-Rehab-Traditional-AR and B-Rehab-AR." (PMID 32916851, 2020). "BDNF is believed to have a beneficial effect on stroke recovery via several mechanisms: increased angiogenesis and neurogenesis, increased brain repair, and enhanced synaptic plasticity." (PMID 31191635, 2019). "This study has demonstrated for the first time that consecutive administration of LIPUS displays a benefit for recurrent stroke via BDNF induction." (PMID 31635269, 2019). "Five days poststroke, an additional cohort of aged stroke animals were treated with intracerebral hydrogels loaded with the BDNF decoy, TrkB-Fc." (PMID 31191635, 2019). "In the present study, the findings have demonstrated that LIPUS treatment arouses the expression of BDNF and possesses a therapeutic benefit for the alleviation of stroke recurrence in a mouse model." (PMID 31635269, 2019). "After a stroke, treatment with brain-derived neurotrophic factor (BDNF) increases functional recovery, whereas reduction of BDNF levels prevented the benefits of rehabilitative training." (PMID 30983963, 2019). "Whilst the therapeutic potential of BDNF has been illustrated in preclinical stroke models, clinical success has been challenged by poor blood-brain barrier (BBB) permeability, short half-life, and off-target effects." (PMID 31191635, 2019). "We showed that the expression of Dlg4, Gria1, Grin2a, Gng3, Gnb5, MapK8, and Bdnf (encoding PSD-95, GluA1, GluNMDA2A, G-protein subunit gamma 3, G-protein subunit beta 5, JNK, and BDNF, respectively) was strongly reduced 1 week after stroke." (PMID 31888302, 2019). "Because a study where brain-derived neurotrophic factor was administered alongside hBMSC in a stroke model showed positive results, variable approaches have been reported to enhance the neurorestorative effect of cell-based therapy." (PMID 31024439, 2019). "It must be noted, however, that stroke-induced increases in endogenous BDNF are insufficient to reverse functional impairments." (PMID 31427916, 2019). "In contrast, stroke to aged mice facilitated a significant improvement in reversal learning, which was dampened in the presence of the BDNF decoy, TrkB-Fc." (PMID 31191635, 2019). "The effects of BDNF and other GFs have previously been investigated in various stroke models and have shown strong regenerative potential." (PMID 31427916, 2019). "Taken together, these results demonstrate for the first time that LIPUS treatment arouses the expression of BDNF and possesses a therapeutic benefit for the improvement of stroke recurrence in a mouse model." (PMID 31635269, 2019).
Stroke (continued). "The expression of BDNF has been demonstrated to have benefits on stroke recovery through several mechanisms and proposed actions including the increase in brain repair, the acceleration of neurogenesis, and the promotion of angiogenesis." (PMID 31635269, 2019). "Evidence from preclinical animal models also supports an age-related difference in expression of BDNF, with stroke inducing a lessened elevation of BDNF in aged mice compared to young stroke controls." (PMID 31427916, 2019). "Collectively, these findings support the idea that BDNF is likely to play a role during the reparative phase after stroke, a period where the brain repairs itself to try compensate for the damaged tissue." (PMID 31191635, 2019). "In particular, BDNF has been highlighted as being a key regulator of rehabilitation-induced recovery after stroke." (PMID 31427916, 2019). "Several empirical studies have indicated the benefits of the increased expression of BDNF or receptor in different stages of stroke such as acute ischemic stroke, the rehabilitation process, and recurrence." (PMID 31635269, 2019). "Studies using in situ hybridization have revealed a stroke-induced upregulation of BDNF mRNA expression in both the ipsilateral cortex and hippocampus in rat models of forebrain ischemia." (PMID 31427916, 2019). "Physical exercise in rehabilitation is thought to increase BDNF levels resulting in a greater capacity for neuronal survival and plasticity after stroke." (PMID 31359356, 2019). "Brain-derived neurotrophic factor (BDNF) is another important neurotropic protein that can be produced by microglia after stroke." (PMID 31447626, 2019). "In the present study of spontaneous recovery we found a late downregulation of BDNF mRNA levels in the stroke-denervated hemicord, corroborating previous studies of protein levels in the cervical spinal cord." (PMID 30962276, 2019). "Astrocytes were seen as the main source of BDNF immunoreactivity in the ipsilateral hemisphere 1 week after stroke." (PMID 31105589, 2019). "With this in mind, studies are underway assessing VD reversal task learning in aged stroke animals that receive recombinant human BDNF (rhBDNF) via a hydrogel implanted into the stroke cavity." (PMID 31191635, 2019). "A promising study from the Carmichael lab investigated the use of a BDNF-loaded hyaluronan-based hydrogel that was cross-linked with PEG, in two mouse models of stroke." (PMID 31427916, 2019). "Nonetheless, BDNF expression remained slightly upregulated in the ipsilateral hemisphere 1 week post-stroke." (PMID 31105589, 2019). "Low intensity pulsed ultrasound (LIPUS) has been demonstrated to possess therapeutic effects on neuronal diseases and stroke via brain-derived neurotrophic factor (BDNF) induction." (PMID 31635269, 2019). "Among all studies included in the current review, however, only one evaluated the effect of aerobic training (running) performed immediately before a reaching task on functional recovery and BDNF levels post-stroke (experimental model)." (PMID 30210424, 2018). "Studies conducted in other animal ischaemia models also showed that BDNF minimizes cell death, decreases the volume of the site of stroke, and accelerates the restoration of neurological status and cognitive abilities." (PMID 30081596, 2018). "Among all 21 studies included in this review, 6 studies evaluated the effects of functional training on BDNF concentration All of them were performed using an experimental stroke model in rats." (PMID 30210424, 2018). "Aerobic exercise promotes changes in central BDNF concentrations post-stroke in animal models and increased serum BDNF concentration in post-stroke patients." (PMID 30322026, 2018). "A study explored the effects of injecting BDNF into the stroke cavity of mice using two different vehicles." (PMID 30486515, 2018).